BCKDK (branched chain keto acid dehydrogenase kinase)
Diseases named in the same sentence as BCKDK in open-access papers (continued):
Sharing a sentence is not in itself a finding about the gene and the disease.
cancer (continued). "There is no doubt that BCKDK plays a critical role in cancer development, but in order to develop effective cancer treatment, it is necessary to clarify which mechanism is responsible." (PMID 39795113, 2024). "Another noteworthy protein, BCKDK, has recently been found to regulate the catabolism of branched chain amino acids (BCAA) and enhance MEK/ERK signal transduction, which is a key pathway driving the growth and proliferation of cancer cells." (PMID 38054015, 2023). "Recent studies have shown that BCKDK regulates the catabolism of branched chain amino acids (BCAA) and enhances MEK/ERK signal transduction, which is the key pathway that drives the growth and proliferation of cancer cells." (PMID 38054015, 2023). "To further verify that the effects of EAAm on cancer cells viability, glycolysis inhibition, ER stress induction, and mTORC1 inhibition were due to the activation of BCAA catabolism, we treated M14 and Hela cells with the BCKDK inhibitor BT2." (PMID 35367410, 2022). "In addition, based on the known functional roles in cancer and the reported classification of the kinase family, PRKD1, PRKD3, BCKDK, PDK2, and CSNK2A2 were considered as potential CCA-relative PKs, which were related to the six overlapped PKs." (PMID 36231050, 2022). "Through this approach, we revealed that downregulated BCKDK inactivated the focal adhesion, ECM-receptor interaction and EGFR (MAPK and PI3K-Akt) signaling pathways, all of which are directly or indirectly related to EMT process in cancer progression." (PMID 32238881, 2020). "The APN-mediated promotion of cancer development is achieved by mediating the phosphorylation of BCKDK on serine 31 and then activating the ERK1/2 signaling pathway through the direct action of BCKDK." (PMID 32457292, 2020). "Finally, given the popularity of cisplatin in treating a wide range of cancers, we expect that cisplatin treatment in combination with LNA inhibitors or BCKDK inhibitors could help minimize the occurrence of unwanted nephrotoxicity incidental to cisplatin while decreasing tumor mass." (PMID 38016961, 2023).
tumor (16 papers, 2020 to 2025). "Essentially, by preventing the tumor from hoarding BCAAs, BCKDK inhibition causes the tumor to over-oxidize BCAAs, which can create an energetic shortfall or metabolic byproducts that stress the cell." (PMID 41502503, 2025). "Moreover, IHC analysis of tumor sections from the mice revealed that BCKDK deficiency significantly reduced Ki‐67 expression, indicating decreased cell proliferation." (PMID 40789057, 2025). "BCKDK was upregulated in TNBC tumour tissues and associated with poor prognosis." (PMID 39025830, 2024). "Since BCKDK regulates the activity of the BCKDH complex to influence BCAAs catabolism, which is tightly linked to tumor progression, we wondered whether BCKDK regulated CRC metastasis in a BCAAs-dependent manner." (PMID 32238881, 2020). "Collectively, these findings highlight the critical role of BCKDK activation in RCC tumor progression." (PMID 40789057, 2025). "Western blot analysis showed increased levels of BCKDK, p‐RNF8S157, and RAD51 proteins in tumor tissues compared to their adjacent normal tissues, suggesting enhanced activity of the BCKDK/p‐RNF8/RAD51 regulatory pathway in clinical tumor tissues." (PMID 40298908, 2025). "In both paired and unpaired RCC samples, BCKDK mRNA expression was consistently higher in tumor tissues than in normal tissues." (PMID 40789057, 2025). "Analysis of subcutaneous tumor tissues from mice demonstrated that BCKDK silencing inhibited AKT/mTOR pathway activation in vivo." (PMID 40789057, 2025). "Extensive evidence underscores the pivotal role of BCKDK beyond regulating BCAA pools in tumor progression." (PMID 40789057, 2025). "The analysis revealed significant upregulation of BCKDK mRNA in various tumor types, including kidney papillary cell carcinoma (KIRP) and kidney renal clear cell carcinoma (KIRC), compared to their corresponding normal tissues." (PMID 40789057, 2025). "Then, clinical RCC and normal tissue samples were collected, and Western blot analysis confirmed that BCKDK expression was notably higher in tumor tissue compared to normal tissue." (PMID 40789057, 2025). "Consistent with previous reports, BCKDK's role as a protein kinase in tumor progression warrants focused attention and further investigation." (PMID 40789057, 2025). "In line with the in vitro findings, BCKDK knockdown markedly inhibited tumor growth in 786‐O cell xenografts." (PMID 40789057, 2025). "As mentioned, in TNBC models, blocking BCKDK (with BT2 or by shRNA) led to slower tumor growth and enhanced the efficacy of chemotherapy." (PMID 41502503, 2025). "Molecularly, this reprogramming involves coordinated changes in transporters (like LAT1), enzymes (BCAT1/2, BCKDH, BCKDK), and signaling pathways (mTORC1 and beyond) that together promote tumor proliferation, survival under stress, and metastasis." (PMID 41502503, 2025). "To further assess the synergistic effect in vivo, we utilized an MMTV‐PyMT mouse TNBC model, which showed an enhanced BCKDK/p‐RNF8/RAD51 axis in tumor tissues compared to normal compartments." (PMID 40298908, 2025). "Consistent with in vitro results, RNF8 phosphorylation and RAD51 protein levels were increased in Olaparib‐treated tumor samples and were rescued by BCKDK knockdown." (PMID 40298908, 2025). "Suggesting that BCKDK participates in cell death regulation through distinct apoptotic pathways across different tumor types." (PMID 40789057, 2025). "We found that the BCKDK knockdown significantly decreased the metastases of tumor cells to the lung after the tail vein injection compared to the control; metastatic nodules were counted by visual observation." (PMID 37460470, 2023). "Then, the expression level of BCKDK was also determined in OC tissue and corresponding tumor adjacent tissue samples." (PMID 35498541, 2022). "Recent studies have identified novel phosphorylation sites on BCKDK that stabilize BCKDK activity and influence tumor cell proliferation and survival." (PMID 34526485, 2021).
tumor (continued). "MEK was indicated to bind with and phosphorylated by BCKDK at the S221 site, thereby activating tumor cell proliferation." (PMID 32238881, 2020). "The role of BCAT1 and BCKDK in BCAAs metabolism and the significant status of BCAT1 in tumor progression, raises several questions: Is there any relationship between BCKDK and BCAT1 in CRC development?" (PMID 32238881, 2020). "Chemo might work better if given after weakening the tumor with a dietary intervention or a BCKDK inhibitor that loads the tumor cells with oxidative stress." (PMID 41502503, 2025). "Prior studies have shown that BCKDK promotes tumor cell proliferation in CRC by activating the MAPK/ERK signaling pathway, leading us to hypothesize a similar role in RCC." (PMID 40789057, 2025). "In colorectal carcinoma, elevated BCKDK expression is not merely a metabolic adaptation but is also associated with poor differentiation, increased tumor aggressiveness, and shortened overall survival." (PMID 40725241, 2025). "Tumor weight in the BCKDK knockdown group was significantly lower than in the control group." (PMID 40789057, 2025). "Moreover, the correlations among BCKDK, p‐RNF8S157, RAD51, and HRR marker p‐RPA32 were validated by IHC staining of patient samples, suggesting that high BCKDK levels in tumor regions exhibit increased DNA repair ability." (PMID 40298908, 2025). "Both in vitro and in vivo data demonstrated that BCKDK promoted tumor proliferation and growth." (PMID 40789057, 2025). "Consistent with in vitro findings, BCKDK depletion led to attenuated tumour growth in vivo." (PMID 39025830, 2024). "Given the significant impact of BCKDK on tumour proliferation, we hypothesised that BCKDK plays a proliferative role through G6PD." (PMID 39025830, 2024). "Notably, the small-molecule inhibitor of BCKDK, 3,6-dichlorobenzo(b)thiophene-2-carboxylic acid, exhibited anti-tumour effects in a patient-derived tumour xenograft model." (PMID 39025830, 2024). "Evidence has shown that targeting BCKDK with small-molecule and allosteric inhibitors could be effective in suppressing tumor cell development." (PMID 37637065, 2023). "BCKDK knockdown decreased the metastatic potential of the tumor cells to a certain degree." (PMID 37460470, 2023). "The increased expression of BCKDK itself in tumour tissue may suggest the use of BCKDKi, particularly considering BCKDK expression has been correlated with reduced survival of patients with CRC and NSCLC." (PMID 36526674, 2023). "Then, growth curve analysis, anchorage-independent cell transformation assays, wound healing assays, cell migration assays, and tumor xenografts were used to test whether BCKDK could promote cell transformation or metastasis." (PMID 35498541, 2022). "Knockdown of BCKDK inhibited OC tumor progression ex vivo and in vivo." (PMID 35498541, 2022). "BCKDK might play an important role in increasing the sensitivity of tumor cells to paclitaxel." (PMID 40438606, 2025). "Additionally, since some tumors might have specific kinases that regulate BCKDK, blocking those kinases (for instance, blocking Src in an HCC where Src activates BCKDK) could be a more tumor-selective way to achieve the same end." (PMID 41502503, 2025). "Notably, our findings suggest that in RCC progression, the BCKDK/AKT/mTOR signaling axis‐mediated pro‐tumor mechanisms represent a molecular pathway distinct from the previously reported BCKDK‐regulated exosomal miR‐125a‐5p/VE‐cadherin axis that activates angiogenesis to facilitate tumor metastasis." (PMID 40789057, 2025). "Therefore, targeting BCKDK-dependent induction of PPP may contribute to the proliferation of tumour cells sensitive to chemotherapy and/or radiotherapy." (PMID 39025830, 2024). "Thus, BCAAs flux remodeling by BCKDK inhibition in TNBC could be a potential therapeutic approach to hinder tumor growth and progression." (PMID 37637065, 2023). "Hence, these data supported the tumor-promoting function of BCKDK in OC." (PMID 35498541, 2022).
tumor (continued). "To explore the therapeutic potential of targeting the BCKDK‐mediate HRR, we investigated its impact on tumor response to DNA damage‐inducing therapies." (PMID 40298908, 2025). "Interestingly, metabolic side effects of BCKDK inhibition might be mitigated by dietary support—if patients on a BCKDK inhibitor up their intake of BCAAs slightly (or overall protein), it might offset losses in normal tissues while still hurting the tumor." (PMID 41502503, 2025). "Targeted inhibition of the BCKDK/AKT significantly enhanced DOX‐induced apoptosis in RCC cells and suppressed tumor growth in vivo." (PMID 40789057, 2025). "The study found that BCAT1 is phosphorylated by BCKDK in glioblastoma, which enhances its activity and stability while inhibiting its degradation mediated by STUB1 ubiquitination, thereby promoting tumor growth." (PMID 40438606, 2025). "Overall, this study identifies a novel oncogenic role for BCKDK in RCC, wherein it promotes tumor progression and drug resistance through AKT phosphorylation and activation of AKT‐related signaling pathways." (PMID 40789057, 2025). "In TNBC, transcription factor MAZ was reported to directly regulate multiple assumed tumor-promoting genes, such as SIPL1 and BCKDK to accelerate progression of TNBC." (PMID 41444950, 2025). "Targeting BCKDK/AKT inhibits the growth of RCC patient‐derived organoids (PDOs), enhances doxorubicin‐induced apoptosis in RCC cells, and suppresses tumor growth in vivo." (PMID 40789057, 2025). "For example, MAZ was reported to up-regulate the expression of BCKDK, a highly expressed gene in TNBC tumor tissues involving in promoting tumorigenesis." (PMID 41444950, 2025). "BCKDK also activates the RAS/RAF/MEK/ERK pathway by phosphorylating MEK, which promotes tumor cell proliferation." (PMID 37637065, 2023). "BCKDK has been depicted to induce constitutive MEK-ERK signaling cascade activation, promoting multiple tumor cell proliferation, invasion, and migration, including colorectal, liver, and ovarian cancer." (PMID 37460470, 2023). "BCKDK gain significantly promoted the proliferation and migration ex vivo, whereas knocked down expression of BCKDK in HO8910-PM OC cells reduced the proliferation and migration ex vivo and inhibited the tumor growth in vivo." (PMID 35498541, 2022). "The results confirmed that the levels of BCKDK, p-MEK1/2 (Ser221), and p-ERK1/2 (T202/Y204) were lower in the tumor tissue of HO8910-PM-shBCKDK mice than in the tumor tissue of HO8910-PM-shMock mice." (PMID 35498541, 2022). "Branched-chain ketoacid dehydrogenase kinase (BCKDK), a regulatory kinase of the rate-limiting enzyme of the BCAA catabolic pathway, is reported to activate RAS/RAF/MEK/ERK signaling to promote tumor cell proliferation." (PMID 34526485, 2021). "Transcriptomic analysis indicates that BCKDK downregulation alters multiple biological processes, including mTOR, ErbB, Hippo, and apoptosis signaling pathways, highlighting its critical role in RCC tumor progression." (PMID 40789057, 2025). "High BCKDK expression was positively correlated with advanced tumor node metastasis (TNM) stages in RCC." (PMID 40789057, 2025). "Furthermore, this work identifies a small molecule inhibitor of BCKDK, GSK180736A, that disrupts its HRR function and exhibits strong tumor suppression when combined with DNA damage‐inducing drugs." (PMID 40298908, 2025). "Furthermore, Spearman correlation analysis revealed relationships between BCKDK/p‐RNF8S157 and various clinicopathological characteristics, including survival time, vital status, clinical stage, and tumor size." (PMID 40298908, 2025). "Furthermore, the expression levels of BCKDK, p-MEK1/2 (Ser221), and p-ERK1/2 (T202/Y204) were tested in dissected tumor tissues." (PMID 35498541, 2022).
tumor (continued). "In addition, there are studies showing that BCKDK and PPM1K make up a ChREBP-regulated node that integrates BCAA and lipid metabolism and promotes BCAAs as a material for fat synthesis for fat cells, which provide energy for tumor growth." (PMID 35498541, 2022). "Branched-chain α-keto acid dehydrogenase kinase (BCKDK), located in the mitochondrial matrix, belongs to the pyruvate dehydrogenase kinase (PDK) family, promotes the proliferation and metastasis of various tumors, and is considered to be a strong therapeutic target for preventing tumor development." (PMID 35498541, 2022). "Since BCKDK was recently identified as a cytosolic kinase regulating hepatic lipid accumulation, future studies will also interrogate metabolic pathways that co-operate with BCAA metabolism to promote tumor growth or compensate for sustaining cell proliferation when BCAA metabolism is inhibited." (PMID 34526485, 2021). "However, the BCKDK protein, in which the phosphorylation of serine 31 was simulated (BCKDKS31D) can phosphorylate and activate ERK1/2 in APN knockout SK-HEP-1 cells, thereby restoring their proliferation and metastatic phenotypes in a liver orthotopic xenograft tumor model." (PMID 32457292, 2020). "BCKDK‐overexpressing and RNF8‐silenced MDA‐468 tumors expressing RNF8WT or RNF8S157D, but not RNF8S157A, could restore tumor volume and mass, under Olaparib treatment." (PMID 40298908, 2025).
metabolic disease (10 papers, 2013 to 2025). A congenital disorder (due to inherited enzyme abnormality) or acquired (due to failure of a metabolically important organ) disorder resulting from an abnormal metabolic process. "BCKDK deficiency is however a very rare inherited metabolic disease; this disorder was described for the first time in 2012 and only a few patients have been reported so far." (PMID 35216372, 2022). "Recent studies in rodents and humans have shown that pharmacological inhibition of BCKDK significantly improved insulin sensitivity, providing a novel therapeutic target for metabolic diseases." (PMID 39389936, 2024). "A newly discovered therapeutic target for treating metabolic disorders secondary to BCAA accumulation is the enzyme branched-chain α-keto acid dehydrogenase kinase (BCKDK)." (PMID 37762992, 2023). "BCKDK, as an important enzyme affecting the metabolism of BCAA, is now recognized as a new therapeutic target for treating metabolic disorders caused by BCAA accumulation." (PMID 35923208, 2022). "Importantly, a retrospective review of the newborn screening results allowed the identification of a strong decrease in BCAA concentrations on dried blood spots, suggesting that BCKDK is a new treatable metabolic disorder probably amenable to newborn screening programs." (PMID 35216372, 2022). "Thus, the inhibition of BCKDK is potentially an effective treatment for metabolic diseases such as NAFLD/NASH and hepatic cancer, and specific inhibitors targeting BCKDK have been explored." (PMID 39795113, 2024).
infection (2 papers, 2022 to 2025). The state of being infected such as from the introduction of a foreign agent such as serum, vaccine, antigenic substance or organism. "The decreased expression of PPM1K may indicate that BCAA utilization and degradation capacity can be reduced under NE infection in chickens; PPM1K can act more sensitively than the BCKDH kinase (BCKDK) and BCKDH enzymes involved in BCAA catabolism do." (PMID 41007887, 2025). "We chose day 21 to screen our serum samples using PhIP-Seq because reports indicate that autoantibodies to some of the known antigens, such as Myhc-α, ANT, and BCKDk, were detected in sera from CVB3-infected animals during the 15- to 28-day post-infection period." (PMID 36101433, 2022).
neurological disorders (1 paper, 2022). "Lacking BCAAs and BCKDK mutations may cause severe neurological disorders and growth retardation." (PMID 35923208, 2022).
BCKDK also shares sentences with these, for which no sentence is quoted: Intellectual disability (5 papers); microcephaly (3); autism spectrum disorder (2); colon cancer (2); Epileptic encephalopathy (2); neurodevelopmental disorder (2); urea cycle disorder (2); Autoimmunity (1); biotinidase deficiency (1); cardiovascular disease (1); congenital heart disease (1); developmental and epileptic encephalopathy (1); diabetic retinopathy (1); Kaufman oculocerebrofacial syndrome (1); methylmalonic acidemia (1); mitochondrial disease (1); organic acidemias (1); overnutrition (1); Parkinsonism (1); primary biliary cirrhosis (1); rectal adenocarcinoma (1); serous ovarian cancer (1); uterine carcinosarcoma (1); viral myocarditis (1).